ACTL6B (actin like 6B)
Description:
Involved in transcriptional activation and repression of select genes by chromatin remodeling (alteration of DNA-nucleosome topology). Component of SWI/SNF chromatin remodeling complexes that carry out key enzymatic activities, changing chromatin structure by altering DNA-histone contacts within a nucleosome in an ATP-dependent manner. Belongs to the neuron-specific chromatin remodeling complex (nBAF complex), as such plays a role in remodeling mononucleosomes in an ATP-dependent fashion, and is required for postmitotic neural development and dendritic outgrowth. During neural development a switch from a stem/progenitor to a postmitotic chromatin remodeling mechanism occurs as neurons exit the cell cycle and become committed to their adult state. The transition from proliferating neural stem/progenitor cells to postmitotic neurons requires a switch in subunit composition of the npBAF and nBAF complexes. As neural progenitors exit mitosis and differentiate into neurons, npBAF complexes which contain ACTL6A/BAF53A and PHF10/BAF45A, are exchanged for homologous alternative ACTL6B/BAF53B and DPF1/BAF45B or DPF3/BAF45C subunits in neuron-specific complexes (nBAF). The npBAF complex is essential for the self-renewal/proliferative capacity of the multipotent neural stem cells. The nBAF complex along with CREST plays a role regulating the activity of genes essential for dendrite growth. ACTL6B/BAF53B is not essential for assembly of the nBAF complex but is required for targeting the complex and CREST to the promoter of genes essential for dendritic growth (By similarity). Essential for neuronal maturation and dendrite development.
Synonyms: BAF53B; ACTL6; SMARCN2; DEE76; EIEE76; IDDSSAD; arpNalpha
Tractability: PROTAC: ubiquitination databases record sites on it; its protein half-life has been measured.
Gene: Protein-coding gene on chromosome 7 (100,643,097 to 100,656,458, reverse strand). Ensembl gene ENSG00000077080.
Subcellular location: Nucleus
Subcellular location (Human Protein Atlas): Nucleoli rim; Mitotic chromosome
Pathways (Reactome):
Chromatin organization: Formation of neuronal progenitor and neuronal BAF (npBAF and nBAF); RMTs methylate histone arginines
Gene expression (Transcription): RUNX1 interacts with co-factors whose precise effect on RUNX1 targets is not known
Gene Ontology:
Molecular function: chromatin binding; structural constituent of cytoskeleton; transcription coactivator activity
Biological process: chromatin remodeling; dendrite development; neuron maturation; chromatin organization; negative regulation of cell differentiation; nervous system development; positive regulation of cell differentiation; positive regulation of cell population proliferation; positive regulation of double-strand break repair; positive regulation of myoblast differentiation; positive regulation of stem cell population maintenance; positive regulation of T cell differentiation; regulation of G0 to G1 transition; regulation of G1/S transition of mitotic cell cycle; regulation of mitotic metaphase/anaphase transition; regulation of nucleotide-excision repair; regulation of transcription by RNA polymerase II; cytoskeleton organization; positive regulation of DNA-templated transcription
Cellular component: nucleus; SWI/SNF complex; bBAF complex; brahma complex; chromatin; GBAF complex; kinetochore; nBAF complex; nuclear matrix; RSC-type complex
Genetic constraint (gnomAD): Loss-of-function variants: 48 observed, 64.01 expected, observed/expected ratio (o/e) 0.75, 90% interval 0.59 to 0.95. The upper end of that interval is the gene's LOEUF score, 0.95, which puts it in group 4 of 6, group 1 being the genes least tolerant of losing a copy. Missense variants: 350 observed, 570.73 expected, observed/expected ratio (o/e) 0.61, 90% interval 0.56 to 0.67. Synonymous variants: 230 observed, 226.01 expected, observed/expected ratio (o/e) 1.02, 90% interval 0.91 to 1.13.
Homologues: Orthologues: chimpanzee ACTL6B (100% identical), macaque ACTL6B (100% identical), dog ACTL6B (99% identical), mouse Actl6b (99% identical), rat Actl6b (99% identical), guinea pig ACTL6B (99% identical), rabbit ACTL6B (95% identical), zebrafish actl6b (86% identical), tropical clawed frog actl6b (48% identical). Paralogues in human: ACTL6A (85% identical), ACTC1 (38% identical), ACTB (38% identical), ACTG1 (38% identical), ACTA2 (38% identical), ACTA1 (38% identical), ACTG2 (38% identical), ACTBL2 (36% identical), ACTR1B (33% identical), ACTR1A (31% identical), ACTR3B (30% identical), ACTR3 (29% identical), and 14 more.
Diseases named in the same sentence as ACTL6B in open-access papers:
ACTL6B is named in the same sentence as 33 diseases in open-access papers, as found by Europe PMC text mining. Sharing a sentence is not in itself a finding about the gene and the disease. The quoted sentences say what the papers report.
epilepsy (5 papers, 2022 to 2026). A brain disorder characterized by episodes of abnormally increased neuronal discharge resulting in transient episodes of sensory or motor neurological dysfunction, or psychic dysfunction. "We find that DEE76, caused by the ACTL6B biallelic variant, is an early-onset drug-refractory epilepsy with global developmental delayHP:0001263, hypertoniaHP:0001276, and microcephalyHP:0000252, and imaging is characterized by brain delayed myelinationHP:0012448." (PMID 36553410, 2022). "Interestingly, among multiple CRF genes, only SMARCA2, SMARCB1, ACTL6B and KDM5C have been previously associated with epilepsy, and some other members of this cluster (e.g., SMARCC1, SMARCC2, SMARCA4 and WRD5) are only cursorily mentioned among epilepsy candidate genes." (PMID 36982355, 2023).
developmental delay (3 papers, 2022 to 2026). "Pathogenic variants of BAF, ACTL6B, are associated with severe forms of DEE with profound developmental delay and intellectual disability." (PMID 39858526, 2025). "Thus, among the clinical signs of ACTL6B variants are intellectual disability, developmental delay, lack of speech, hypomyelination, agenesis of the corpus callosum, and severe epilepsy." (PMID 39858526, 2025).
Intellectual disability (1 paper, 2025). "Thus, loss of ACTL6B function reduces the ability of neurons to form synaptic connections and leads to impaired neuronal differentiation, which plays a critical role in DEE pathology and intellectual disability." (PMID 39858526, 2025).
malignant rhabdoid tumors (1 paper, 2025). "In malignant rhabdoid tumors (MRTs), aberrant co-expression of ACTL6A and ACTL6B is observed, accompanied by altered DNA methylation at differentiation-associated genes and at the neuronal marker NeuN." (PMID 41514521, 2025).
neuroblastoma (1 paper, 2016). Neuroblastoma (NB) is the most common solid, extracranial childhood tumor. "In contrast, two neuroblastoma cell lines, IMR-32 and KELLY, had an unmethylated ACTL6B promoter, and ACTL6B was expressed." (PMID 26812616, 2016).
Neurodevelopmental delay (1 paper, 2024). "Mutations in the BAF subunit ACTL6B (actin-like protein 6B) cause neurodevelopmental delay and epilepsy encephalopathy likely via a loss of dendrites and an increase in neuronal hyperexcitability." (PMID 38927072, 2024).
prostate adenocarcinoma (1 paper, 2020). "In prostate adenocarcinoma cells, we observed that short-term REST knock-down led to an increase of BAF53B (ACTL6B) mRNA and protein levels, but the effect was modest, while other neuronal genes known to be negatively controlled by REST (e.g., synaptophysin) were highly upregulated." (PMID 33144576, 2020).
cancer (2 papers, 2019 to 2020). A tumor composed of atypical neoplastic, often pleomorphic cells that invade other tissues. "The role of ACTL6B in neuronal development and differentiation has been analyzed; however, studies in cancer are missing." (PMID 31769422, 2019). "ACTL6B, a paralog of ACTL6A, has not been studied extensively in cancer." (PMID 31769422, 2019).
tumor (2 papers, 2016). "The association between somatic mutations of the SWI/SNF complex, also ACTL6B methylation, and tumor characteristics was analyzed." (PMID 26812616, 2016).
ACTL6B also shares sentences with these, for which no sentence is quoted: Anxiety (2 papers); neurodevelopmental disorder (2); adenocarcinoma (1); Angelman syndrome (1); Aphasia (1); astrocytoma (1); autism spectrum disorder (1); chronic intestinal pseudo-obstruction (1); Coffin-Siris syndrome (1); Developmental and epileptic encephalopathy-76 (1); Dystonia (1); endotoxemia (1); gastric cancer (1); generalized cerebral atrophy (1); Helsmoortel van der Aa syndrome (1); hepatocellular carcinoma (1); hyperlipidemia (1); invasive breast carcinoma (1); microcephaly (1); Obesity (1); ovarian carcinoma (1); pancreatic cancers (1); Rett syndrome (1); tauopathy (1).